SLC26A6 (solute carrier family 26 member 6)
Description:
Apical membrane anion-exchanger with wide epithelial distribution that plays a role as a component of the pH buffering system for maintaining acid-base homeostasis. Acts as a versatile DIDS-sensitive inorganic and organic anion transporter that mediates the uptake of monovalent anions like chloride, bicarbonate, formate and hydroxyl ion and divalent anions like sulfate and oxalate. Functions in multiple exchange modes involving pairs of these anions, which include chloride-bicarbonate, chloride-oxalate, oxalate-formate, oxalate-sulfate and chloride-formate exchange. Apical membrane chloride-bicarbonate exchanger that mediates luminal chloride absorption and bicarbonate secretion by the small intestinal brush border membrane and contributes to intracellular pH regulation in the duodenal upper villous epithelium during proton-coupled peptide absorption, possibly by providing a bicarbonate import pathway. Also mediates intestinal chloride absorption and oxalate secretion, thereby preventing hyperoxaluria and calcium oxalate urolithiasis. Transepithelial oxalate secretion, chloride-formate, chloride-oxalate and chloride-bicarbonate transport activities in the duodenum are inhibited by PKC activation in a calcium-independent manner. The apical membrane chloride-bicarbonate exchanger also provides a major route for fluid and bicarbonate secretion into the proximal tubules of the kidney as well as into the proximal part of the interlobular pancreatic ductal tree, where it mediates electrogenic chloride-bicarbonate exchange with a chloride-bicarbonate stoichiometry of 1:2, and hence will dilute and alkalinize protein-rich acinar secretion. Also mediates the transcellular sulfate absorption and oxalate secretion across the apical membrane in the duodenum and the formate ion efflux at the apical brush border of cells in the proximal tubules of kidney. Plays a role in sperm capacitation by increasing intracellular pH. [Isoform 4]: Apical membrane chloride-bicarbonate exchanger. Its association with carbonic anhydrase CA2 forms a bicarbonate transport metabolon; hence maximizes the local concentration of bicarbonate at the transporter site.
Synonyms: DKFZp586E1422
Tractability: Antibody: UniProt places it where antibodies can reach, with high confidence; its Gene Ontology location is reachable by antibodies, with high confidence; UniProt predicts a signal peptide or a membrane-spanning region; the Human Protein Atlas places it where antibodies can reach. PROTAC: ubiquitination databases record sites on it.
Gene: Protein-coding gene on chromosome 3 (48,625,718 to 48,635,493, reverse strand). Ensembl gene ENSG00000225697.
Subcellular location: Cell membrane; Apical cell membrane; Cytoplasmic vesicle membrane; Microsome; Cell membrane (Isoform 4); Basolateral cell membrane; Cell membrane (Isoform 5); Cell membrane (Isoform 6)
Subcellular location (Human Protein Atlas): Plasma membrane; Cytosol
Pathways (Reactome):
Transport of small molecules: Inorganic anion exchange by SLC26 transporters
Gene Ontology:
Molecular function: chloride:bicarbonate antiporter activity; oxalate transmembrane transporter activity; solute:inorganic anion antiporter activity; efflux transmembrane transporter activity; formate transmembrane transporter activity; PDZ domain binding; sulfate transmembrane transporter activity; secondary active sulfate transmembrane transporter activity
Biological process: bicarbonate transport; cellular response to type II interferon; chloride transport; oxalate transport; regulation of intracellular pH; sulfate transmembrane transport; transepithelial chloride transport; cellular response to cAMP; cellular response to fructose stimulus; chloride transmembrane transport; epithelial fluid transport; formate transport; intestinal absorption; intracellular pH elevation; mannitol transmembrane transport; oxalic acid secretion; positive regulation of dipeptide transmembrane transport; sperm capacitation; transepithelial transport; transmembrane transport; estrous cycle
Cellular component: apical plasma membrane; basolateral plasma membrane; brush border membrane; membrane; plasma membrane; cytoplasmic vesicle membrane; sperm midpiece; vesicle; vesicle membrane
Genetic constraint (gnomAD): Loss-of-function variants: 67 observed, 88.14 expected, observed/expected ratio (o/e) 0.76, 90% interval 0.62 to 0.93. The upper end of that interval is the gene's LOEUF score, 0.93, which puts it in group 3 of 6, group 1 being the genes least tolerant of losing a copy. Missense variants: 902 observed, 992.96 expected, observed/expected ratio (o/e) 0.91, 90% interval 0.86 to 0.96. Synonymous variants: 414 observed, 414.06 expected, observed/expected ratio (o/e) 1, 90% interval 0.92 to 1.09.
Homologues: Orthologues: chimpanzee SLC26A6 (96% identical), macaque SLC26A6 (95% identical), pig SLC26A6 (81% identical), dog SLC26A6 (80% identical), mouse Slc26a6 (77% identical), rabbit SLC26A6 (77% identical), rat Slc26a6 (75% identical), guinea pig SLC26A6 (75% identical), tropical clawed frog slc26a6 (51% identical), tropical clawed frog slc26a6 (46% identical), zebrafish slc26a6l1 (46% identical), zebrafish slc26a6l2 (45% identical), and 1 more. Paralogues in human: SLC26A5 (38% identical), SLC26A4 (37% identical), SLC26A3 (35% identical), SLC26A9 (35% identical), SLC26A2 (30% identical), SLC26A1 (30% identical), SLC26A8 (28% identical), SLC26A7 (25% identical), SLC26A11 (22% identical).